STC2 (stanniocalcin 2)
Diseases named in the same sentence as STC2 in open-access papers (continued):
Sharing a sentence is not in itself a finding about the gene and the disease.
cancer (continued). "Therefore, STC2 is an indispensable factor to control post-radiation proliferation, survival and migration; and STC2 is a promising target for developing a novel therapy to overcome radiation resistance in human cancers." (PMID 35501821, 2022). "STC2, a mammalian stanniocalcin, is located on chromosome 5q35.1 and is involved in a variety of biological processes, including calcium regulation, cell proliferation and apoptosis, inflammation, endoplasmic reticulum/oxidative stress, metabolism, and cancer processes." (PMID 34599150, 2021). "In addition, STC2 had inconsistent effect on cell proliferation of different cancers." (PMID 37287492, 2021). "Finally, STC2's role as a novel marker for human cancers has also been outlined." (PMID 32296395, 2020). "Notably, STC2 was reported to mediate drug resistance, which was a key factor in cancer treatment." (PMID 32258098, 2019). "Therefore, the function of STC2 in the development of some cancers remains controversial." (PMID 32258098, 2019). "However, different correlations between STC2 expression and cancer progression have been reported." (PMID 25830567, 2015). "Numerous studies have reported that the STC2 gene can be epigenetically modified and the expression of STC2 may be regulated by stimulation of hypoxia and/or endoplasmic reticulum (ER) stress in human cancers." (PMID 25830567, 2015). "To support their possible roles in crucial oncogenic mechanisms, we assessed the mutation frequency, copy number amplification, and copy number–expression correlation of STC2, MIF, CD74, CXCR4, GDF15, and TGFBR2 across several cancer types." (PMID 41502509, 2025). "Stanniocalcin-2 (STC2), a glycoprotein involved in calcium homeostasis and cellular stress responses, is frequently overexpressed in various human cancers." (PMID 40006048, 2025). "This knowledge is relevant as both STC2 and PAPP-A appear to be involved in diseases affecting elderly individuals, e.g. cancer and cardiovascular disease." (PMID 37334305, 2023). "Next, Pan-Cancer Expression Landscape of STC2 showed that STC2 exhibited inconsistent expression across 26 types of human cancer, lower in KIRP in cancer versus adjacent normal tissues, and significantly higher in another cancers." (PMID 36685853, 2022). "From our best research, HOXC6, SLC2A4, VIP, CD1A, STC2, and OLFM2 are related to cancer progression." (PMID 35711425, 2022). "STC2 promotes the proliferation, tumorigenicity, and epithelial-mesenchymal transition (EMT) via PI3K/AKT or AKT-ERK signaling in several types of cancer." (PMID 35790735, 2022). "As for the relationship between the expression of STC2 and the clinical and pathological stages of tumors, we found that the differential expression of STC2 was related to stage, grade and TMN staging in majority of cancer types." (PMID 36685853, 2022). "In LAML, BRCA LUSC, PCPG, and UVM, STC2 were highly expressed in males than those in females, while it were less expressed in males than those in females with KIRP, KIPAN and LIHC cancers." (PMID 36685853, 2022). "The results of RT-PCR indicated that GPC1, STC2, P4HA4, and ENO3 were upregulated in cancer cells while SPAG4 was downregulated in the five cancer cells." (PMID 33747908, 2021). "STC2 and SLC2A1 were both involved in biological behaviors of many cancers, especially in HCC, through the modulation of mTOR signaling pathways." (PMID 34194464, 2021). "Among the 12 hypoxia-inducible genes in irradiated BALB/c, both HIF1α and STC2, a HIF1A target gene, were overexpressed in human cancers and pre-neoplastic breast lesions." (PMID 23077491, 2012). "Moreover, STC2's involvement in modulating the immune landscape within the TME suggests its potential as a target for immunotherapy, offering new avenues for cancer treatment." (PMID 40535801, 2025).
cancer (continued). "STC2 is significantly correlates with immune stimulator genes in most cancers, except BRCA, CESC, LUAD, LUSC, TCGT and THCA; STC2 is significantly correlates with immune inhibitory genes in most cancers, except BRCA, LUSC, TGCT and THCA." (PMID 40535801, 2025). "Additionally, we performed experimental research and found STC2 is significantly upregulated in CRC tissue and can promote CRC progression by regulating cancer cell invasion and proliferation." (PMID 40535801, 2025). "STC2 expression was mainly observed in endothelial cells, normal epithelial cells, and cancer epithelial cells, while FLT3 was primarily expressed in myeloid cells and cancer epithelial cells." (PMID 39020010, 2024). "Moreover, we found that TPD52, TF, and CCT6A were more frequently heterozygous amplified while STC2, CISD1, and P4HA2 were more likely to occur in heterozygous deletion in cancers." (PMID 36998462, 2023). "STC2 activates ITGB2/FAK/SOX6 and PI3K–AKT signaling pathways in some cancers." (PMID 35937984, 2022). "Researchers employed immunohistochemistry to analyze the clinical significance of STC2 and found that STC2 levels were higher in cancer tissues than in matched non-cancerous tissues." (PMID 36685853, 2022). "It has been demonstrated a link between the calcium-related functions of STC2 and cancer, however, STC2-overexpressing transgenic mice having normal serum Ca2+ and phosphate levels, as well as STC2 knockout mice exhibiting no changes in serum Ca2+." (PMID 35790735, 2022). "Therefore the intracellular expression and secretion level of STC2 are increased in the occurrence process from normal epithelial cells to TAE which was gradually obtained EMT-like phenotypes, even induced into cancer cells." (PMID 27662663, 2016). "In BRCA, BLCA, ESCA, COADREAD and READ, STC2 is expressed differentially between patients over 65 years of age and patients under 65 years of age, while this age correlation has not been observed in other cancers." (PMID 36685853, 2022). "And STC2 could significantly activate the mitogen-activated protein kinase (MAPK) and phosphatidylinositol 3-kinase/protein kinase B (PI3K/AKT) signaling pathways in some cancers." (PMID 32258098, 2019). "Functional studies have not been carried out to fully reveal the impact of STC2 in cancer cells." (PMID 25830567, 2015).
infection (5 papers, 2018 to 2024). The state of being infected such as from the introduction of a foreign agent such as serum, vaccine, antigenic substance or organism. "The DEGs involved in amino acid biosynthesis and energy metabolic processes were GOT1, CBSL, SOCS1, LPL and STC2, and their expressions were largely down‐regulated in response to H37Rv infection." (PMID 34632719, 2021). "Considering NF-κB is activated by various cell injury, pathogen infection and inflammatory signaling, we deduce that STC2 could also be induced by a variety of stress including cell injury and inflammatory factors." (PMID 38464261, 2024). "Considering NF-κB is activated by various cell injury, pathogen infection and inflammatory signalling, we deduce that STC2 could also be induced by a variety of stress, including cell injury and inflammatory factors." (PMID 39107307, 2024).
metabolic disease (3 papers, 2017 to 2024). A congenital disorder (due to inherited enzyme abnormality) or acquired (due to failure of a metabolically important organ) disorder resulting from an abnormal metabolic process. "Given that STC2 treatment improved metabolic disorders in ob/ob mice, the mRNA levels of adipogenic genes, hepatic gluconeogenic genes, hepatic triglyceride synthesis related genes were analyzed in ob/ob mice." (PMID 29207625, 2017). "Together, our results revealed an important role of STC2 in the regulation of hepatic triglyceride metabolism, which might provide a potential therapeutic target for the treatment of fatty liver and related metabolic disorders." (PMID 30038584, 2018).
digestive system tumors (1 paper, 2022). "STC2 is a useful molecular marker predicting the progression and prognosis of digestive system tumors, including hepatocellular carcinoma, pancreatic cancer, gastric cancer, and colorectal cancer." (PMID 35937984, 2022).
retinopathy (1 paper, 2025). "Later on, we described reduced expression of STC2 in DM2 patients, who often exhibit a prothrombotic status that underlies retinopathy and diabetic feet, among other hallmarks." (PMID 41155293, 2025).
STC2 also shares sentences with these, for which no sentence is quoted: sarcoma (4 papers); bladder cancer (3); cervical squamous cell carcinoma (3); thymoma (3); cardiovascular disease (2); cholangiocarcinoma (2); colorectal tumor (2); endometriosis (2); gallbladder cancer (2); lung squamous cell carcinoma (2); pheochromocytoma (2); renal papillary cell carcinoma (2); type 2 diabetes mellitus (2); acute lymphoblastic leukemia (1); Ascites (1); bacterial infection (1); Brachycephaly (1); Cerebral ischemia (1); chondrosarcoma (1); colon adenoma (1); deep venous thrombosis (1); diffuse large B-cell lymphoma (1); endocervical adenocarcinoma (1); Glucose intolerance (1); gynecologic cancers (1); heart failure (1); Hypertension (1); Impaired glucose tolerance (1); Infertility (1); inflammatory bowel disease (1).
A further 25 diseases each share a sentence with STC2 in 1 paper.